TNF (tumor necrosis factor)
Diseases named in the same sentence as TNF in open-access papers (continued):
Sharing a sentence is not in itself a finding about the gene and the disease.
gout (continued). "The results of the MR analysis with good sensitivity suggested a causal relationship between candidate genes (KCNA5, PTGS2, and TNF) and gout, in which high levels of PTGS2 increase the hazard of gout, while KCNA5 and TNF can diminish the occurrence of gout." (PMID 40430440, 2025). "Although IL-1β plays a crucial role in the pathogenesis of the pathogenesis of gout flares, other cytokines such as IL-6, TNF-α, and TGF-β are also involved in that." (PMID 38240927, 2024). "Prior investigations reported that MSU-triggered inflammation induces gout formation, whereas PA promotes anti-inflammatory activities that diminish IL-6, C-reactive protein, and TNF." (PMID 39060811, 2024). "Cytokine levels, including IFN-γ, TNF-α, IL-2, IL-4, IL-6, IL-10 and IL-17, were detected in early-onset gout, late-onset gout and HCs." (PMID 38240927, 2024). "As a pro-inflammatory cytokine, TNF-α aggravates the inflammatory response of neutrophils and functions as a key factor in gout generation and persistence." (PMID 39170709, 2024). "These therapeutic effects are attributed to bioactive compounds, including cucurbitacins, flavonoids, and alkaloids, which inhibit key pro-inflammatory mediators like TNF-α, IL-1β, and IL-6—cytokines involved in the inflammatory response during gout attacks." (PMID 39409183, 2024). "When comparing the upregulated DEGs of CMs and IMs between gout flare and remission, we observed enrichment in pathways including mineral absorption, together with IL-17, TNF, and TLR signaling." (PMID 38063198, 2023). "In our study, plasma cytokines including IL-1β, IL-6 and IL-10 were significantly higher in RA than OA, while TNFα was higher in gout than RA." (PMID 37202736, 2023). "Patients with RA had higher plasma levels of sTNFR1, IL-1β, IL-12p70, TNF and IL-6, compared to OA and gout patients (all, P < 0.05)." (PMID 37202736, 2023). "Gallic acid is reported to suppress TNF-α and IL-1β levels in gouty arthritis mice model by inhibiting NLR family pyrin domain containing 3 (NLRP3) inflammasome activation." (PMID 36899361, 2023). "Febuxostat is a drug used for the treatment of gout that has anti-inflammatory properties, by inhibiting TNF-α and IL6, along with antioxidant and antifibrotic roles." (PMID 37763811, 2023). "MSU can directly stimulate monocytes/macrophages to regulate the release of inflammatory factors such as TNF-α, IL-1β, and IL-18, thereby promoting gout inflammatory response." (PMID 36673346, 2023). "A study on human blood monocytes and synovial cells found that urate crystals stimulate the production of TNF-α, which is involved in the inflammatory process of gouty arthritis." (PMID 37881185, 2023). "Plasma levels of pro-inflammatory cytokines IL-1β, IL-6, IL-12p70 and TNF were elevated in RA patients in contrast to OA and gout, with significant differences between RA and OA groups (p < 0.05)." (PMID 37202736, 2023). "A case report indicated that the TNF-α antagonist etanercept combined with febuxostat showed efficacy for refractory gout." (PMID 37734872, 2023). "While screening for flavonoids with anti-gout effects, Hao found that luteolin can ameliorate hyperuricaemia and acute gouty arthritis by reducing the levels of inflammatory factors (TNF-α, IL-1β) in rats." (PMID 35924042, 2022). "ELISA analysis showed that the gout group significantly up-regulated the levels of IL-1β, Caspase-1, IL-6 and TNF-α, and significantly decreased the levels of IL-10, which were induced by MSU (p < 0.05)." (PMID 36313318, 2022). "Subsequently, neutrophils predominate at the inflammatory site and represent a significant cell population contributor to the pathology of gout through the release of pro-inflammatory mediators, such as IL-1β, TNF-α, or NETs and proteases." (PMID 36496970, 2022). "It has been reported that TNF-α monoclonal antibody Infliximab and Adamuzumab were applied in RA patients and also benefit refractory gout patients." (PMID 36248423, 2022).
gout (continued). "In turn, neutrophils interact with MSU crystals and induce the release of IL-1, IL-6, TNF-α, and other cytokines, resulting in pain and erythema related to gout flare." (PMID 34586567, 2022). "The main inflammatory cells in gouty arthritis attacks are mononuclear macrophages and multinucleated macrophages, which produce various cytokines such as tumor necrosis factor-α (TNF-α)." (PMID 36297105, 2022). "Research demonstrated that multiple pro-inflammatory cytokines, such as IL-6 and TNF-α, are related to gouty arthritis." (PMID 34586567, 2022). "A patient with RA used anti-TNF (etanercept), a patient with AS used NSAIDs, a patient with gout used colchicine and allopurinol." (PMID 36422487, 2022). "Effects of total extract of Lagotis brachystachya on serum TNF-α, IL-1β, and IL-6 of rats with chronic alcoholic liver injury and gouty arthritis (x ± s, n = 8)." (PMID 36176434, 2022). "In general, the prevalence of fever in gout is driven by specific pyrogens (IL-1, IL-6, tumor necrosis factor (TNF)-α) with the inflammasome as a pivotal activator of the inflammatory cascade." (PMID 33926105, 2021). "TNF-α is a well-known proinflammatory cytokine with a major role in the pathogenesis of several diseases, including gout." (PMID 33926105, 2021). "Accumulating studies have shown that TNF-α and IL-1β are closely related to the pathogenesis of gouty arthritis." (PMID 34803702, 2021). "β-Caryophyllene decreased the productions of TNF and IL-6 in the serum of gout rats, thus relieving inflammation symptoms." (PMID 33967792, 2021). "The results clearly showed that SHA treatment suppressed the major inflammatory cytokines (TNF-α and IL-1β), which are essential in the initiation and progression of gouty arthritis." (PMID 34284768, 2021). "An extract of Tu-Teng-Cao (TTC) can inhibit the secretion of cytokines TNF-α and IL-6 in synovial fluid of rats, reduce ankle joint damage, and control uric acid and inflammation to treat gouty arthritis." (PMID 34721646, 2021). "Collectively, our results indicate that SHA has inhibitory effects on inflammation and gouty arthritis primarily by intervening in the formation of inflammasomes and lessening the proinflammatory cytokines of TNF-α and IL-1β." (PMID 34284768, 2021). "High levels of cytokines such as interleukin 1 (IL-1β), IL-63, IL-85, and tumor necrosis factor α (TNFα) have been detected in the synovial fluid of gout patients." (PMID 34567284, 2021). "Polarization into the M1 phenotype promotes the production of proinflammatory cytokines IL-1β and TNF-α that further aggravate gout." (PMID 33505510, 2021). "Our results showed that the expression of IL-1β, TNF-α, and IL-6 was increased in the gouty rats, and the inhibitory effect of BV was similar to or better than that of Col, a treatment drug for acute gouty arthritis." (PMID 34564665, 2021). "Clinical studies have shown that the TNF-α inhibitor etanercept can significantly improve the clinical manifestations and laboratory results of gouty arthritis." (PMID 33149752, 2020). "The concentrations of TNF-α, IL-6, IL-1β and sIgA in colon tissue (N=7/group) were notably increased in the experimental model of gouty arthritis compared with those of the normal control mice." (PMID 32670069, 2020). "These inflammatory cytokines (IL-6, IL-8, IL-1β, and TNF-α) exert differential effects on vascular inflammation and dysfunction in patients with gout, a condition characterized by hyperuricemia." (PMID 33330657, 2020). "The carrageenan-induced paw edema is another experiment model of gout that involves several inflammatory mediators such as TNF-α and IL-1 β." (PMID 33299636, 2020). "Both chronic hyperuricemia and gout involve inflammation responses and stimulate the release of interleukin-1β, interleukin-6 (IL-6), tumor necrosis factor-α (TNF- α), NF-kβ, and activate the NALP3 inflammasome complex." (PMID 32687535, 2020).
gout (continued). "Numerous studies have investigated the relationship between cherry and gout or uric acid; however, the focus has been on the anti-inflammatory effects of IL-1 β and TNF-α, which are used as biomarkers in monitoring acute gout flare ups." (PMID 31885677, 2019). "IL-1β can activate other proinflammatory cytokines, including tumor necrosis factor-α (TNF-α) which is critical for the initiation and propagation of the inflammatory response in gouty arthritis." (PMID 31885675, 2019). "Nonetheless, we found higher plasma levels of IL-1β, IL-1ra, IL-4, IL-6, IL-8, IL-9, IL-13, IL-17, FGF-basic, IFNγ, and TNFα in acute gouty arthritis patients." (PMID 31739430, 2019). "We herein report a case of Chlamydia-induced ReA diagnosed during gout flares that was successfully treated with a tumor necrosis factor (TNF) inhibitor." (PMID 31577714, 2019). "Consistently, TNFα and IL-lβ also induced the up-regulation of IL-33 expression in the synovial fibroblasts from gout patients." (PMID 30863362, 2019). "The gene expression of IL-1β and TNF-α, typical pro-inflammatory cytokines present in gout, was enhanced in BMDMs after exposure to MSU crystals at 4 h and 8 h, and their expression was higher in BMDMs from miR-146a KO mice than WT mice." (PMID 29544526, 2018). "Our present results also showed the significant production of pro-inflammatory cytokines, including IL-1β and TNF-α, in monocytes from patients with gout." (PMID 29056937, 2017). "In the one study of 957 older Italians free of renal disease or gout, having higher uric acid was associated with increased neutrophils, CRP, IL-1ra, IL-6, IL-18 and TNFα." (PMID 28786993, 2017). "We found endogenous ALPK1, myosin IIA, and plasma TNF-α were higher among gout patients than healthy controls (p < 0.01)." (PMID 27169898, 2016). "The levels of TNF-α and IL-1β in the ankle joint lavage fluid were elevated markedly in the gouty arthritis model group when compared with the control group (P < 0.05)." (PMID 26989428, 2016). "Such glucocorticoid-independent effects of ACTH have been demonstrated after lipo-polysaccharide (LPS)-stimulated production of IL-1ß and TNF-α in human blood samples, in a rat gout model, and in TNF-α-induced acute kidney disease in rats." (PMID 27199894, 2016). "The findings suggest ALPK1 is a kinase that participates in the regulation of Golgi-derived TNF-α trafficking through myosin IIA phosphorylation in the inflammation of gout." (PMID 27169898, 2016). "Infiltration of the synovium by neutrophils is considered to be characteristic of gouty inflammation, and the development of acute inflammation in gout requires the participation of IL-17-related cytokines (IL-1, IL-6, IL-8, and TNF-α)." (PMID 26890073, 2016). "In patients with gout, the pro-inflammatory cytokines such as IL-1β, IL-6 and TNF-α can reduce the synthesis and secretion of apolipoprotein in hepatocytes by affecting HMG-CoA reductase, leading to reduced levels of lipids and lipoprotein levels." (PMID 24068523, 2014). "Differences in efficacy among agents in another class of anti-cytokine therapy, TNF-α antagonists, have been demonstrated to be related to such factors in arthritic diseases other than gout." (PMID 23375025, 2013). "Indomethacin, a drug often used as first-line therapies for acute inflammation in gouty arthritis, also reduced the TNF-α and IL-1β mRNA and protein levels in rats induced by MSU crystal." (PMID 23304232, 2012). "Furthermore, TNF-α is another key pro-inflammatory cytokine that contributes significantly to the exacerbation of gout attacks." (PMID 40388724, 2025). "Specifically, we identified multiple CIPs, including FGF21, MMP-1, G-CSF, IFN-γ, CXCL1, IL-1Ra, and TNF-α, which may serve as potential molecular therapeutic targets for gout." (PMID 40388724, 2025). "Additionally, IL‐1β and TNF‐α immunofluorescence dual staining in gout and gout post‐OA synovial organoids was performed and imaged by laser confocal imaging." (PMID 39764563, 2025).
gout (continued). "Mice with gout model supplemented with butyrate showed significant reductions in the foot thickness ratio and the levels of inflammatory factors (IL-1β, IL-6, and TNF-α) in their foot tissue." (PMID 39907694, 2025). "TNF-α orchestrates gout pathogenesis through dual-phase immunometabolic crosstalk." (PMID 40388724, 2025). "KCNA5, PTGS2, and TNF were identified as crucial targets for Bi-Qi capsules in the treatment of gout, which might provide new evidence for the future clinical application of Bi-Qi capsules." (PMID 40430440, 2025). "Consequently, reduced BA levels promote the production of pro-inflammatory cytokines (IL-17 and TNF-α), thereby exacerbating inflammatory responses in gout." (PMID 41255527, 2025). "This inverse expression pattern in gout patients suggests that alterations in the TNF-α/NF-κB signaling pathway could serve as a key marker for differentiating between these two conditions." (PMID 40370447, 2025). "Tumor necrosis factor α (TNF-α) is pivotal in gout pathogenesis." (PMID 40612947, 2025). "Previous studies have exhibited that honeysuckle polysaccharides could exert anti-gout activity by downregulating the levels of inflammatory factors IL-1β, IL-6, and TNF-α in the serum of mice in a sodium urate-induced gouty arthritis model." (PMID 40942068, 2025). "Moreover, in the HUA and gouty arthritis models, IL-1β and TNF-α secretion into the mouse serum was significantly greater than that in the vehicle group." (PMID 38708084, 2024). "For example, targeting the JAK2/STAT3 signaling pathway could reduce the expression of pro-inflammatory cytokines like IL-6, IL-1β, and TNF-α, thereby alleviating gout symptoms and slowing disease progression." (PMID 39611154, 2024). "TNF-α, IL-6, and IL-1β are involved in the activation and maintenance of inflammatory responses, which serve key roles in the development and sustenance of gouty arthritis." (PMID 36824696, 2023). "Furthermore, the ABCG2 gene played a crucial role in the aberrant generation of pro-inflammatory cytokines such as interleukin-1 beta (IL-1β), tumor necrosis factor-alpha (TNF-α) and IL-8 in gout." (PMID 36967798, 2023). "Moreover, asymptomatic hyperuricemia population present the same level of IL‐1β and TNF‐α compared with patients with gout flare, highlighting the importance of physicians paying special attention to asymptomatic hyperuricemia." (PMID 36988248, 2023). "Our analysis revealed a significant reduction of IFN-γ- and TNF-α- producing Vδ2 T cells in gout." (PMID 37714974, 2023). "TNF-α is one of the important inflammatory factors in gouty arthritis." (PMID 36673346, 2023). "Patients with gout have significantly elevated levels of TNF-α." (PMID 37734872, 2023). "In TNF signaling, TNF-α is an inflammatory mediator in gouty arthritis, which could be released by MSU crystal stimulation." (PMID 36248423, 2022). "Dapansutrile may reduce the inflammatory response and the chemotaxis of inflammatory cells by blocking the activation of IL1B, CXCL8, and TNF for the treatment of gouty arthritis." (PMID 36105284, 2022). "Moreover, a higher level of aggregated neutrophils and tumor necrosis factor α were observed in the tophus of gout patients." (PMID 36555994, 2022). "Furthermore, the TNF-α is involved in the expression of pro-IL-1β mRNA and IL-1β protein in gout, triggering the MSU-induced inflammation in mice." (PMID 34359507, 2021). "Indeed, TNF-α directly promotes the expression of IL-1β protein and pro-IL-1β mRNA transcription in a mouse model of gout, and blocks TNF-α resulting in a dramatic amelioration of inflammation." (PMID 33959014, 2021). "This inhibition might reduce the levels of proinflammatory factors (TNF-α and IL-1β) and alleviates the inflammatory response in gouty arthritis." (PMID 34803702, 2021).
gout (continued). "As a result, various cytokines and chemokines are released, and in particular, IL-1β and TNF-α promote the recruitment of neutrophils, resulting in the inflammation of gouty arthritis through the release of a large amount of proinflammatory substances such as IL-1β, TNF-α, and IL-6." (PMID 34564665, 2021). "Studies have shown that the combination of TNF-α, GM-CSF and MSU will cause neutrophils to produce IL-8 and eliminate the release of MIP-1α, leading to the recruitment of neutrophils, which is consistent with the pathological state of gout." (PMID 35116032, 2021). "A recent randomized, double-blind, placebo-controlled pilot study showed a positive correlation between UA serum levels and IL-6, IL-17, and TNF-α, suggesting that xanthine oxidase inhibitors reduce levels of serum UA but also of these cytokines in patients with gout." (PMID 35237183, 2021). "This suggests that plantain may be a potential treatment for gout and hyperuricemia by inhibiting TNF signaling pathway." (PMID 33149752, 2020). "Conversely, IL-1α, IL-6, IL-12(p40), G-CSF, MCP-1, and TNF-α, which could be induced by gouty arthritis, were significantly reduced by Simiao decoction and febuxostat." (PMID 32670069, 2020). "The pathogenesis of gouty arthritis has also been correlated with IL-1β via TNF-α, and NLRP3 inflammasome activation in macrophages and chemokines and an IL-1β antibody has been shown to provide superior inflammation prophylaxis than colchicine in patients with gout." (PMID 30854012, 2019). "Immunologically, the T-cell pathway associated with interleukin-6, interleukin-8, and tumor necrosis factor is enhanced in patients with gout, irrespective of acute or chronic status." (PMID 30634389, 2019). "Moreover, 6-shogaol was documented to alleviate monosodium urate crystal-induced gouty arthritis and decrease the lysosomal enzymatic activity and the TNF-α level in mice." (PMID 29466287, 2018). "Moreover, studies have confirmed that elevated levels of IL-1β and TNF-α can be detected in the blood of rats with gout and those of the hyperuricemia model." (PMID 30410553, 2018). "Notably, after stimulation with LPS, substantial amounts of IL-1β, IL-8, and TNF-α were detected in patients with gout." (PMID 29056937, 2017). "Some signatures of metabolome in male gout patients have been reported being involving in inflammation, such as acetate that regulates T cells, IL-8, TNF-α and 1L-1β through binding GPR43, succinate that induces IL-1β through HIF-1α and glucose that regulates T cell activation." (PMID 28270806, 2017). "This beneficial anti-gouty arthritis effect may be mediated, at least in part, by inhibiting the production of IL-1β and TNF-α." (PMID 28623927, 2017). "In addition, monocytes from gout patients exhibited anti-inflammatory as well as pro-inflammatory activity, demonstrated by the production of IL-1β, IL-8, TNF-α, and IL-10." (PMID 29056937, 2017). "TNF-α and IL-1β are thought to be particularly important in the pathogenesis of gouty arthritis." (PMID 26989428, 2016). "Here, we found that HG could significantly decrease the increased expression of TNF-α and IL-1β in rats with gouty arthritis." (PMID 26989428, 2016). "We conclude that RPP15 may be a promising candidate for the development of a new treatment for gout and its activity of antigout may be partially related to inhibiting TNF-α, IL-1β, IL-8, and NF-κB p65 expression in the synovial tissues." (PMID 26221174, 2015). "In addition, IL-1β can induce the expression of a wide range of cytokines and chemokines like TNF-α, IL-6, IL-17, and MCP-1 that are directly responsible for the influx of neutrophils into the synovium, a hallmark of gouty arthritis." (PMID 26709520, 2015). "The increased concentration of plasma ox-LDL might be related to the increase of IL-6 and TNF-α leading to increased generation of peroxides in gout patients." (PMID 24068523, 2014).